IL21 (interleukin 21)
Diseases named in the same sentence as IL21 in open-access papers (continued):
Sharing a sentence is not in itself a finding about the gene and the disease.
lupus (continued). "IL-21 is overproduced in intestinal inflammation, psoriasis, type I diabetes, systemic lupus erythematosus (SLE), and RA." (PMID 33515210, 2021). "Combining this novel alternating-antigen immunization strategy and rapid humanization approach yielded an IL-21 neutralizing antibody that is currently under clinical development for the treatment of Systemic Lupus Erythematosus (SLE)." (PMID 30682117, 2019). "There is compelling evidence that blockades of cytokines, including BAFF, BCMA, APRIL, IL-6, and/or IL-21, inhibit B cell proliferation in murine lupus." (PMID 31795353, 2019). "BXSB-Yaa lupus-prone mice showed higher circulating IL-21 and its mRNA transcripts compared with wild-type mice, and deletion of IL-21R would abrogate characteristic lupus phenotypes such as autoantibodies production and glomerulonephritis in these mice." (PMID 31835612, 2019). "In a recent study, inhibition of Treg cell differentiation and IL-21 has been found to repress rapamycin axis via suppression of autophagy in lupus patients." (PMID 30108582, 2018). "The number of Tfh cells as well as the level of IL-21 has been shown to be increased in lupus-prone mice and SLE patients." (PMID 29556239, 2018). "High serum levels of IL-21 were also detected in BXSB-Yaa mice, and blockade of the IL-21/IL-21R pathway slows the progression of lupus by decreasing lymphocyte activation and circulating IgG1 levels in BXSB-Yaa mice." (PMID 30123218, 2018). "In sanroque mice, the number of Tfh cells is increased with the hyperactive ICOS signaling and excessive production of IL-21, leading to the development of spontaneous GC formation and lupus-like autoimmune phenotypes." (PMID 30123218, 2018). "In lupus MRL/lpr mice, activated CD4+ T cells secrete 10 times more IL-21 than control mice and IL-21R deficiency leads to reduced numbers of TFH cells." (PMID 27635407, 2016). "IL-21 production is increased e.g. in patients with systemic lupus erythematosus, and rheumatoid arthritis." (PMID 26934574, 2016). "The real-time PCR analysis of skin biopsies taken from 3 lupus patients also revealed that IL-21 transcripts were significantly increased compared to control individuals." (PMID 27635407, 2016). "IL-21 gene polymorphisms have been reported to be associated with an increasing number of autoimmune or immunological diseases, including systemic lupus erythematosus (SLE), rheumatoid arthritis, GD and type 1 diabetes." (PMID 24944624, 2014). "Sanroque mice develop lupus-like autoimmunity that is associated with greatly increased numbers of CD4+CXCR5+ T cells and enhanced expression of IL-21." (PMID 23638156, 2013). "Subsequent investigations demonstrated that blocking of the IL-21 pathway reduces levels of anti-dsDNA autoantibodies and prevents renal disease in mouse models of systemic lupus erythematosus (SLE)." (PMID 23799890, 2013). "For example, in lupus, the IL-21 producing T cells have been shown to be increased, while the IL-21R expression on B cells appears to be decreased or unchanged." (PMID 23496892, 2013). "In summary, our results confirm that both Tfh cells and B10 cells are expanded in MRL/lpr mice and that Tfh cell-derived IL-21 is one of potent inducers for IL-10 production during the differentiation of B10 cells in a lupus animal model." (PMID 23638156, 2013). "Blocking the IL-21/IL-21R pathway by administration of a fusion protein has been fruitful in animal models of RA and in a lupus-prone MRL-Faslpr mouse model." (PMID 21959034, 2011). "Inhibiting the IL-21/IL-21R pathway has been shown to be effective in ameliorating disease severity in lupus mouse models." (PMID 21959034, 2011). "Serum IL-21 levels in 40 primary SS, 40 rheumatoid arthritis (RA), and 38 systemic lupus erythematosus (SLE) patients and 20 healthy controls were measured." (PMID 22030011, 2011).
lupus (continued). "Other interesting reports have shown that in vivo neutralization of IL-21 can lead to decreased rheumatoid arthritis in rats and lupus development in mice, as well inhibition of matrix metalloproteinase secretion in inflammatory bowel disease." (PMID 18773086, 2008). "Disrupted roquin in sanroque mice leads to over-expression of ICOS and IL-21 in T cells, unrestrained formation of follicular helper T cells, autoantibody production and lupus phenotype." (PMID 16563187, 2006). "IL-21 and IRF5 enhanced the generation of ABCs in lupus-associated SWEF-deficient mice." (PMID 39960645, 2025). "Considerable evidence advocates for suppressing cytokines like BCMA, BAFF, IL-6, and IL-21 to inhibit B cell expansion in murine lupus, but it remains essential to explore how these interventions may influence the aging-related dynamics of B cell populations." (PMID 38398810, 2024). "IL-21 was found to drive the expansion of autoreactive plasma cells in human lupus patients." (PMID 37339051, 2023). "Conversely, blockade of IL-21 signaling reduced disease progression in lupus-prone mice." (PMID 37339051, 2023). "Baicalin and TLR7 agonist imiquimod treatment could relieve lupus mice by inhibiting Tfh cell differentiation and IL-21 production, and promoting Tfr cell differentiation." (PMID 37187757, 2023). "Moreover, increased expression of IL-2, IL-21, and IL-22 in lupus mice was downregulated by GDF-15 treatment." (PMID 35911685, 2022). "The blockade of IL-21/IL-21R is currently investigated in lupus (NCT03371251) and could be of interest in ITP." (PMID 33801294, 2021). "In addition, TFH cells are expanded in lupus-prone mice and lead to an increase in IL-21 production." (PMID 33632240, 2021). "Given the accumulating evidence on a vital role of IL-21 in regulating CD11c+ABCs in lupus patients, it is likely that enhanced IL-21 signaling in salivary gland may promote CD11c+ABCs functions in the pathogenesis of pSS." (PMID 34168653, 2021). "Furthermore, IL-21 serum levels were shown to positively correlate with disease severity in lupus patients." (PMID 30013031, 2018). "Moreover, IL-21 blockade and ablation of IL-21 signaling in lupus-prone mice ameliorate disease symptoms by reducing total B cells, plasmablasts and autoantibody titers." (PMID 30266981, 2018). "Accumulating evidence has shown that dysregulation of Tfh cells and IL-21 could result in disordered autoimmunity, contributing to various autoimmune diseases, such as systemic lupus erythematosus (SLE) and ankylosing spondylitis (AS)." (PMID 30157931, 2018). "For example, SLE is a heterogeneous disease, and lupus patients might be either predominated by IL-17a and/or IL-21 expression." (PMID 30108582, 2018). "Both IL-21 and IFN-γ have been implicated in lupus pathogenesis." (PMID 29593732, 2018). "In contrast, IL-21 blockade successfully ameliorates lupus symptoms in lupus-prone MRL mice." (PMID 28456914, 2017). "In addition to IL-21, therapeutic targeting of other GC cytokines has a beneficial effect on mouse models of Lupus." (PMID 31557986, 2016). "Since T cells of systemic lupus erythematosus patients are characterized by enhanced IL-21 transcription, this might also be of functional relevance in humans." (PMID 28066428, 2016). "Furthermore, the percentages of CD4+ T cells producing IL-21 are significantly enhanced in lupus patients." (PMID 27635407, 2016). "We recently found that purified B cells from T cell-deficient BXSB.Yaa mice as young as 4 weeks of age have a lupus-like “IFN signature” that develops in the absence of IL21." (PMID 27050763, 2016). "Indeed, elevated IL-21 expression drives pathogenic autoantibody production in BXSB-Yaa and in the MRL-Fas(lpr) mouse lupus models." (PMID 25961061, 2015). "Our recent study proved that Tfh cell-derived IL-21 could promote the differentiation of Breg cells in lupus-prone MRL/lpr mice, however the relationship between Tfh and Breg cells in SLE patients is not known." (PMID 24551101, 2014).
lupus (continued). "As a result, IL-21 antagonism is worthy of consideration for the treatment of lupus in humans." (PMID 23638156, 2013). "Together, these data indicate that Tfh cell-derived IL-21 may be one of promoting factors for IL-10 production in lupus, which is consistent with the recently Nature published results that IL-21 is important for B10 cell development and expansion." (PMID 23638156, 2013). "Our finding that IL-21-induced IL-10 production provided, at least in part, an explanation for the elevated IL-10 in lupus suggested that micro-environmental cytokines or factors may be involved in the development of B10 cells and autoimmune regulation." (PMID 23638156, 2013). "Thus, selective targeting of Tfh cells and IL-21 for the treatment of lupus requires careful consideration due to the multifactorial nature of these regulatory T cells." (PMID 23638156, 2013). "Blockade of IL-21 with IL-21R-Fc fusion protein has resulted in fewer IgG glomerular deposits, circulating dsDNA auto-antibodies, total sera IgG1, IgG2a and lymphadenopathy in the lupus-prone MRL-Faslpr mouse." (PMID 23176102, 2012). "Elevated levels of circulating Tfh-like cells and IL-21 have been observed in patients with systemic lupus erythematosus (SLE) and rheumatoid arthritis (RA) correlating strongly with disease severity and autoantibody levels." (PMID 40283219, 2025). "Clearly, given the role that IL-21 plays in mediating both types of immunity, any imbalance in its regulation (and in its receptor) could lead to autoimmune diseases, as in the case of animal models with type 1 diabetes or systemic lupus erythematosus." (PMID 37759505, 2023). "Genetic polymorphisms may contribute to the abnormalities noted in nonlesional skin, as, for example, susceptibility to lupus is in part associated with polymorphisms in the IL-21 axis and polymorphisms in IL-17 are correlated with PSO treatment response." (PMID 35486723, 2022). "Therefore, the increase in IL21 in lupus-prone mice could favor the generation of autoreactive plasma cells and the increase in autoantibodies." (PMID 33763492, 2021). "In MRL/lpr mice, the abnormally high expression of Tfh‐associated molecules, such as ICOS, PD‐1, BCL‐6 and IL‐21, suggests that Tfh cells may play a crucial role in the pathogenesis of SLE, which is closely connected with autoantibody production and/or lupus‐like symptoms." (PMID 34318604, 2021). "T cells from SLE patients and lupus-prone mice have expanded T helper 1 (Th1), Th17, follicular, and extrafollicular helper T (Tfh and eTfh) cell subsets, which contribute to the inflammation and autoreactive antibody production through increased IFNγ, TNFα, IL-6, IL-17, and IL-21 secretion." (PMID 32849532, 2020). "Serum IL-21 levels were found to be elevated in patients with SLE, especially in patients with lupus nephritis, and to correlate with disease severity." (PMID 27635407, 2016). "Several studies reported the role of IL-21 in the pathogenesis of systemic lupus erythematosus (SLE) and rheumatoid arthritis (RA)." (PMID 26416419, 2015). "Several observations indicate an important role of IL-21-driven B cell responses in autoimmune syndromes such as systemic lupus erythematosus (SLE)." (PMID 25961061, 2015). "Therefore, it is tempting to speculate that inhibitors of IL-21 may be useful to attenuate lupus-related clinical manifestations." (PMID 23638156, 2013). "Follicular helper T cells (Tfh), a critical subset of CD4+ T cells in lupus, are characterized by high expression of CXCR5, PD-1, interleukin-21 (IL-21), and the specific transcription factor BCL6." (PMID 40989817, 2025). "This suggested that in the lupus-like context, TFH cells are more prone to provide IL-21 to surrounding cells in these mouse models." (PMID 38649353, 2024). "IL21, a pro-inflammatory cytokine principally produced by immune cells, plays a pivotal role in inflammatory and autoimmune conditions like arthritis and systemic lupus erythematosus (SLE)." (PMID 38728237, 2024).
lupus (continued). "Studies found that type I IFN signals inhibited Tfh cell expansion, but induced Tph cell generation and IL-21 and IFNγ production in Tfh cells by activating STAT4 in lupus mice." (PMID 37187757, 2023). "IL-21 was found to be crucial for ABC development in the SWAP-70 and DEF6 double knock-out (DKO) model of lupus as well as the E.muris infection model." (PMID 36072594, 2022). "It has been shown that Tfh cells could secrete IL-21 and thus facilitate Breg cell differentiation and production of IL-10 in systemic lupus erythematosus (SLE)." (PMID 36339942, 2022). "Percentages of CD8+, CD11b+, CD19+, CD11C+ cells, TH2 cells, and pro-inflammatory cytokines (IL-1β, IL-2, IL-4, IL-21, and IL-22) were reduced after GDF-15 treatment in lupus mice." (PMID 35911685, 2022). "In skin lesions, higher mRNA levels of AIM2 and TFH‐related genes, including BCL6, IL21 and STAT3, were found in lupus patients than in NCs." (PMID 35343082, 2022). "Our previous work also showed that lupus patients with positive anti-dsDNA antibody titer and higher disease activity (SLEDAI score ≥ 6) have elevated percentages of IL-21-producing cTFH cells." (PMID 36293075, 2022). "In our present study, based on mice models, we found that GDF-15 alleviated lupus by reducing renal damage, reversing CD8+, CD19+, and TH2 cells dysregulation, inhibiting production of IL-1β, IL-2, IL-4, IL-21, IL-22, ANA, and total IgG." (PMID 35911685, 2022). "Studying systemic lupus erythematosus (SLE), Kato and Perl showed that IL-21, identified as a key proinflamamtory cytokine in this disease, stimulated both TORC-1 and−2, and abrogated differentiation as well as function of Tregs along with autophagy, a phenomenon underlying Treg dysfunction in SLE." (PMID 31191553, 2019). "ABCs are generated through the interplay of IL-4, IL-21, and IFN-γ in concert with TLR engagement, and have been shown to play a role in the pathogenesis of lupus-like autoimmunity and anti-viral immunity." (PMID 28953967, 2017). "Furthermore, these data imply that lupus develops under the complex regulation of Tfh cells as well as diverse B-cell subsets, and thus, exclusive selective targeting of Tfh cells and IL-21 for the treatment of lupus may be a double-edged sword and deserves additional investigation." (PMID 23638156, 2013). "Here, we investigated the percentages of Tfh cells and B10 cells in lupus-prone MRL/Mp-lpr/lpr (MRL/lpr) mice and examined the effects and mechanism of Tfh cell-derived interleukin-21 (IL-21) on IL-10 production during the differentiation of B10 cells." (PMID 23638156, 2013). "In particular, IL-21 drives an inflammatory T-cell response by triggering the production of IL-17, which is thought to be a crucial cytokine for inflammatory processes as occur in lupus nephritis in SLE." (PMID 21959034, 2011). "Ab-01, a human antibody generated by phage display, recognizes the high affinity receptor for IL-21, IL21R, blocks IL21-mediated immune activation through antagonist engagement of IL21R and has shown efficacy in a mouse model of lupus." (PMID 20509950, 2010). "In this context, various autoimmune diseases—such as systemic lupus erythematosus (SLE) and rheumatoid arthritis (RA)—may be induced—for instance, the serum levels of pro-inflammatory cytokine IL-21 are elevated in patients with SLE, correlating with disease activity." (PMID 40771819, 2025). "Therefore, TLR7 and TLR9 signals and IL-21 and IFN-γ play critical roles in ABC differentiation in lupus mice." (PMID 39960645, 2025). "Further studies in lupus-prone MRL/Mp-lpr/lpr (MRL/lpr) and B6.Sle1.Yaa mice revealed a beneficial effect after IL-21 neutralization in autoantibody production and also reduced renal-infiltrating Tfh and Th1 cells, improved renal histology, and reduced GC B cells and CD138hi plasmablasts." (PMID 40283219, 2025).
lupus (continued). "Altogether, these results strongly suggest that in the lupus-like context basophils in SLO enable TFH cell accumulation, increase TFH cell ability to produce IL-21 and IL-4 and promote TFH cell function including B cell isotype switch and plasmablast differentiation." (PMID 38649353, 2024). "By GSVA using lupus-relevant murine gene sets, MRL/lpr mice showed increased enrichment of a number of inflammatory cell and cytokine gene sets including T cells, myeloid cells, neutrophils, pDCs, IFN, IL1, IL21, and TNF." (PMID 38860651, 2024). "It was noted that in pathologies such as lupus or rheumatoid arthritis, the number of CD4+ T lymphocytes producing IL-21 increased, suggesting that blocking this IL could improve the conditions of these pathologies." (PMID 37759505, 2023). "Moreover, IL-21, produced mainly by activated CD4+ T-cells, appeared to up-regulate miR-7 and miR-22 in both healthy and lupus B-cells, providing a positive feedback between activated T-cells and B-cells in lupus patients." (PMID 37215992, 2023). "As BCL-6, IL-21, CD40L and ICOS are all critical regulators involved in the differentiation and maturation of Tfh cells, these findings are helpful for understanding the role that Tfh cells play in lupus." (PMID 35637283, 2022). "In addition to IL-21, IFN-γ has been shown to promote the generation of CD11c+T-bet+ ABCs upon Influenza and E.muris infection as well as in a WAS chimera lupus model." (PMID 36072594, 2022). "IL-21 is markedly elevated in autoimmune-prone mice and lupus severity is diminished in the absence of IL-21 or IL-21R signaling." (PMID 31057553, 2019). "Mice that have a single-amino-acid mutation in Roquin1 (a negative regulator of ICOS mRNA stability) demonstrate a spontaneous lupus-like phenotype that is accompanied by elevated numbers of Tfh cells expressing higher level of ICOS, IFN-γ OX40, and IL-21 and activated phenotypes of GCs." (PMID 30158933, 2018). "Secretion of IL-17, IL-21, and IL-22 by TH17 cells correlates with the pathogenesis of several autoimmune (rheumatoid arthritis, systemic lupus erythematosus, multiple sclerosis, and psoriasis) and inflammatory diseases (inflammatory bowel disease and allergy and asthma)." (PMID 29632528, 2018). "Another interesting model to study lupus-related pathophysiology is the BXSB mouse model, which displays lymphoid hyperplasia, monocytosis, immune complex-mediated glomerulonephritis, and an aberrant IL-21-dependent Tfh response." (PMID 30158933, 2018). "Other evidences come from studies on IL-21, the main cytokine produced by TFH, in lupus mice." (PMID 27635407, 2016). "One recent study was also able to show increased Tfr cell numbers as well as decreased Tfh cell numbers in the absence of IL-21 signaling in lupus-prone BXD2 mice, further highlighting the important role of IL-21 on CD4+ T cells in the GC reaction." (PMID 31557986, 2016). "In the context of T follicular helper (TFH) cell-mediated systemic lupus erythematosus (SLE), AIM2 was found to promote TFH cell differentiation and IL-21 production via the c-myofascial fibrosarcoma (c-MAF) signaling pathway." (PMID 39600708, 2024). "First, the proportions of spleen TFH cells producing IL-21 without any restimulation were significantly increased in both lupus-like models and further amplified after phorbol myristate acetate (PMA) and ionomycin restimulation as compared to spleen TFH cells from control mice." (PMID 38649353, 2024). "There is a super-functional Tfh-like cells subset in lupus-prone New Zealand Black x New Zealand White (NZBxW) mice, defined as IL-21+IFN-γhighPD-1lowCD40LhighCXCR5−Bcl-6− T cells, which express high levels of TNF-α and IL-2 and help B cells to produce IgG in an IL-21 and CD40L-dependent manner." (PMID 38051200, 2024).